SUZ12 (SUZ12 polycomb repressive complex 2 subunit)
Diseases named in the same sentence as SUZ12 in open-access papers (continued):
Sharing a sentence is not in itself a finding about the gene and the disease.
ovarian carcinoma (9 papers, 2017 to 2025). A malignant neoplasm originating from the surface ovarian epithelium. "High SUZ12 protein expression was detected in 76.9% of ovarian cancer tissues (90/117), and this rate was higher than the high expression rate in the normal ovarian epithelium (20.0%, 7/35) and fallopian tube epithelium (13.3%, 2/15); this phenotype was also correlated with poor OS." (PMID 39400513, 2024).
Weaver syndrome (9 papers, 2019 to 2025). Weaver syndrome (WVS) is a rare, multisystem disorder characterized by tall stature, a typical facial appearance (hypertelorism, retrognathia) and variable intellectual disability. "EZH2, EED2, and SUZ12 mutations cause the neurodevelopmental disorders Weaver syndrome (OMIM #277590), Cohen-Gibson syndrome (OMIM #617561), and Imagawa-Matsumoto syndrome (OMIM #618786)." (PMID 38690732, 2024). "Similar to EZH2, several mutations in EED have also been identified in patients with Weaver syndrome, while mutations in SUZ12 have been associated with a Weaver-like syndrome presenting with macrocephaly, postnatal overgrowth, and skeletal abnormalities." (PMID 36845425, 2023). "In humans, heterozygous mutations in the EZH2, EED and SUZ12 genes cause congenital overgrowth, often marked by features that are typical of those observed in Weaver syndrome." (PMID 31575610, 2019). "Each of these PRC2-related overgrowth syndromes presents with tall stature, macrocephaly, advanced bone age, and intellectual disability, and Weaver syndrome and SUZ12-related overgrowth have been linked to increased risk of hematological malignancies and other cancers." (PMID 36814905, 2023). "Likewise, two of three reported Weaver syndrome-associated mutations in SUZ12 are nonsynonymous substitutions within its VEFS domain, a key functional domain for its association with EZH2 and EED, which, when deleted, abolishes the enzymatic activity of PRC2." (PMID 31575610, 2019). "The rare Weaver syndrome linked to developmental cognitive deficits is caused by autosomal dominant mutations in any one of the three PRC2 core components EZH2, EED and SUZ12." (PMID 37842084, 2023). "Some rare human genetic diseases, associated with prenatal and postnatal overgrowth, are known as PRC2-related overgrowth syndromes (Weaver syndrome, Cohen–Gibson syndrome, and SUZ12-related overgrowth)." (PMID 35918713, 2022). "Germline heterozygous mutations in the genes encoding core PRC2 members (EZH2, EED and SUZ12), NSD1 and DNMT3A have been implicated in a triad of highly phenotypically related human developmental disorders: Weaver syndrome, Sotos syndrome and Tatton-Brown–Rahman syndrome, respectively." (PMID 31575610, 2019). "Weaver syndrome (MIM #277590) is an autosomal dominant condition caused by germline monoallelic mutations affecting the genes encoding the core PRC2 subunits, EZH2, EED and SUZ12." (PMID 31575610, 2019).
leukemia (8 papers, 2013 to 2022). A malignant (clonal) hematologic disorder, involving hematopoietic stem cells and characterized by the presence of primitive or atypical myeloid or lymphoid cells in the bone marrow and the blood. "The H3K27me3 levels were also very low in an MPNST (row 2) as well as a pancreatic cancer (row 3) with loss of two suz12 alleles, and a leukemia with loss of three suz12 alleles (row 5)." (PMID 32651197, 2020). "The suz12-deficient fish with multiple tumor foci either presented distinct malignancies (e.g. leukemia and MPNST) or multiple MPNST foci in distinct anatomic locations, so that a clear separation of these foci could be confirmed by histology." (PMID 32651197, 2020). "Notably, Leukemia 1 cells also over-express a number of chromatin regulators, including Brd3 and Polycomb complex members Ezh2 and Suz12, all of which have been linked with leukemia and other cancers." (PMID 25517911, 2014). "In the p53m/m, nf1b−/−, nf1a+/+, suz12-mutant population, 22 of the 24 tumor-bearing fish (91.7%) had MPNSTs, five displayed leukemia (20.8%), and a single fish showed soft tissue sarcoma or adenosarcoma (4.2%)." (PMID 32651197, 2020). "Mutations in SUZ12 are annotated in 35 tumor types in the AACR Genie database (v4.0), which include MPNST, pancreatic cancer, leukemia and soft tissue sarcoma." (PMID 32651197, 2020). "Meanwhile, Shi and coworkers reported that shRNA-mediated suppression of SUZ12 lead to proliferation arrest and initiation of differentiation of leukemia cells, and had minimal effects on the growth of several non-leukemia-transformed hematopoietic cell lines." (PMID 26017281, 2015). "Ridinge and colleagues reporeted that SUZ12 bound to the Bim promoter represses Bim pro-apoptotic factor transcription, thus inhibiting mitochondrial apoptosis of leukemia cells." (PMID 26017281, 2015). "In the study, we constructed an ARE/SUZ12 dual-specific TK/GCV system for blast phase leukemia gene therapy." (PMID 26017281, 2015). "Both Suz12 and Znf198 associate with promyelocytic leukemia (PML) nuclear bodies (NBs); Suz12 and Znf198 knockdown cell lines exhibit reduced numbers of PML NBs." (PMID 23507839, 2013). "Moreover, we present a model of suz12 LOF-induced leukemia, soft tissue sarcoma and pancreatic adenocarcinoma, which will aid in preclinical studies of these diseases." (PMID 32651197, 2020). "Interestingly, shRNA-mediated inhibition of PRC2 subunit EED, SUZ12, or EZH1/EZH2 causes leukemia cells to stop proliferation and differentiation." (PMID 32436117, 2020). "Likely tight and augmented TK regulation by ARE/SUZ12 composite components may help eradicate leukemia cells." (PMID 26017281, 2015). "High constitutive expression of SUZ12 has been reported to drive proliferation, impair differentiation, and disrupt histone modification, which induces deregulation of transcriptional networks and aggressive leukemia." (PMID 26017281, 2015). "Etv6 and Runx1 are known leukemic regulators, and Suz12 and Ezh2 are core members of the Polycomb repressive complex 2 (PRC2), whose activities have been shown to be essential for MLL-AF9 driven leukemia." (PMID 25517911, 2014). "In addition to solid tumors, SUZ12 and EZH2 were previously identified as tumor suppressor genes in leukemia." (PMID 32651197, 2020).
lymphoma (7 papers, 2014 to 2024). A malignant (clonal) proliferation of B- lymphocytes or T- lymphocytes which involves the lymph nodes, bone marrow and/or extranodal sites. "Interestingly, the expression of PRC2 components EZH2, EED, and SUZ12 was lower in CD19+ normal B-cells as compared to that in lymphoma cell lines." (PMID 32850364, 2020). "Individual examination of the EZH2, SUZ12, and EED genes showed that CRPC and prostate neuroendocrine carcinoma demonstrated an association with frequent alterations in each of the PRC2 encoding genes, while in GCB-DLBCL lymphoma a high correlation was found only with alterations in the EZH2 gene." (PMID 34202528, 2021). "This suggests that GOF mutations in the SET domain of EZH2 can augment the sensitivity of lymphoma cells to the inhibition of either EZH2, SUZ12, or EED." (PMID 34202528, 2021). "Many lymphoma cases showed high expression of EZH2, SUZ12, H3K27me3, and BMI1 in the tumor nuclei." (PMID 28412742, 2017).
Intellectual disability (6 papers, 2021 to 2025). "Importantly, patients with pathogenic variants located within SUZ12 exhibit pre- and postnatal overgrowth, facial dysmorphic features, musculoskeletal abnormalities and developmental delay/intellectual disability." (PMID 34681033, 2021). "For example, variants in PRC2 members EED, SUZ12 and EZH2 share a similar DNAm signature, and a similar clinical spectrum characterised by overgrowth and intellectual disability." (PMID 39843918, 2025). "Germline heterozygous SUZ12 variants cause Imagawa–Matsumoto syndrome (IMMAS, OMIM#618786), which presents with less severe overgrowth and intellectual disability than WVS and COGIS." (PMID 41153408, 2025). "Since intellectual disability is quite common in patients with mutations of genes encoding PRC2 components, it is likely that the loss of SUZ12 contributes to the cognitive disabilities and severe developmental delay seen in patients with type 1 NF1 deletions hemizygous for SUZ12." (PMID 34681033, 2021).
Cognitive impairment (5 papers, 2018 to 2025). Abnormal cognition is characterized by deficits in thinking, reasoning, or remembering. "miR-214-5p reduces contents of serum inflammatory factors and alleviates the cognitive impairment by targeting SUZ12 in Alzheimer's disease mice." (PMID 35799645, 2022).
head and neck squamous cell carcinoma (5 papers, 2018 to 2025). A squamous cell carcinoma that arises from any of the following anatomic sites: lip and oral cavity, nasal cavity, paranasal sinuses, pharynx, larynx, and salivary glands. "Additionally, EED and SUZ12 are upregulated in multiple cancers, including lymphoma, breast cancer, head, and neck squamous cell carcinoma (NHSCC), and colorectal cancer." (PMID 36076977, 2022). "In contrast, in the study of head and neck squamous cell carcinoma (HNSCC) and non-small cell lung cancer (NSCLC), it was found that shRNA-mediated SUZ12 knock-down significantly inhibited tumor cell proliferation, migration and invasion." (PMID 32436117, 2020).
Imagawa-Matsumoto syndrome (5 papers, 2023 to 2025). "Pathogenic SUZ12 variants are causative for the Imagawa-Matsumoto syndrome (IMMAS) and pathogenic variants in EED cause the Cohen Gibson Syndrome (COGIS)." (PMID 38894719, 2024).
lung adenocarcinoma (5 papers, 2021 to 2025). A carcinoma that arises from the lung and is characterized by the presence of malignant glandular epithelial cells. "Correlation of SUZ12 and Bax expressions in human lung adenocarcinoma tissue." (PMID 39400513, 2024). "SUZ12-mediated H3K27me3 modification inhibits HDAC1 expression, and modulate docetaxel resistance in lung adenocarcinoma to." (PMID 40949882, 2025). "SUZ12 is one of the core members of the polycomb repressive complex 2 (PRC2), but its expression and role in lung adenocarcinoma (LUAD) are unclear." (PMID 39400513, 2024).
melanoma (5 papers, 2014 to 2025). A malignant, usually aggressive tumor composed of atypical, neoplastic melanocytes. "We found that, compared to other transcription factors, SUZ12 has been found to have a more significant impact on regulating the expression of genes associated with metastatic-melanoma." (PMID 39820173, 2025). "This highlights the potential importance of targeting SUZ12 as a therapeutic strategy in the treatment of melanoma." (PMID 39820173, 2025). "The investigation revealed that SUZ12, SOX2, TCF3, NANOG and SMAD4 are the maximum chief TFs that control the largest number of genes associated with metastatic-melanoma." (PMID 39820173, 2025). "Human melanoma patients with decreased EED or SUZ12 mRNA have decreased overall survival." (PMID 35223844, 2022). "Moreover, SUZ12 loss can elevate expression of Hox genes such as HOXC13, which is implicated in metastatic dissemination in melanoma, another tumor in which SUZ12 LOF often cooperates with NF1 loss." (PMID 32651197, 2020). "Five hub genes including CXCL11, ICAM1, LEF1, MITF, and STAT1 were identified, SUZ12, SOX2, TCF3, NANOG, and SMAD4 were determined as the most significant TFs in metastatic-melanoma." (PMID 39820173, 2025). "Melanoma cases were found to contain homozygous and heterozygous deletions in EZH2, SUZ12, and EED, and cases with these alterations frequently had decreased mRNA levels of the deleted gene." (PMID 35223844, 2022). "We identified a proportion of melanoma cases which harbored chromosomal amplifications and gains of regions including EZH2, SUZ12, and EED." (PMID 35223844, 2022).
neuroblastoma (5 papers, 2012 to 2024). Neuroblastoma (NB) is the most common solid, extracranial childhood tumor. "E3 altered the interaction of SUZ12, LSD1, and DNMT1 with ERα in endometrial cells and altered the interaction of TET2 and DNMT1 with ERα and ERβ in neuroblastoma cells." (PMID 35491423, 2022). "Altered expression of PcG proteins, such as EZH2, SUZ12 and BMI1, are found in numerous cancer types, such as prostate, breast, liver and neuroblastomas, to name a few." (PMID 33912356, 2019).
T-cell acute lymphoblastic leukemia (5 papers, 2016 to 2025). Acute lymphoblastic leukemia of T-cell origin. "Mechanistically, loss of SUZ12 function has been reported to promote angiogenesis and tumor progression in T-cell acute lymphoblastic leukemia (T-ALL) through modulation of the VEGF signaling pathway." (PMID 41306918, 2025). "Loss-of-function mutations in EZH2, EED, or SUZ12 occur in a subset of myeloid malignancies, T-cell acute lymphoblastic leukemia (T-ALL), and malignant peripheral nerve sheath tumors (MPNSTs)." (PMID 37051671, 2023). "In T-cell acute lymphoblastic leukemia (T-ALL), SUZ12 mutations activate oncogenic signaling pathways, increasing sensitivity to HDAC6 inhibitors." (PMID 40949882, 2025).
acute lymphoblastic leukemia (4 papers, 2020 to 2025). Leukemia with an acute onset, characterized by the presence of lymphoblasts in the bone marrow and the peripheral blood. "Loss-of-function mutations in EZH2 and SUZ12 also have been found in early T-cell precursor (ETP) acute lymphoblastic leukemia (ETP-ALL) and non-ETP T-ALL in children and T-ALL in adults." (PMID 33374737, 2020). "Moreover, in tumoral conditions, in T-cell acute lymphoblastic leukemia (T-ALL), we have seen loss-of function mutations and deletions affecting EZH2 and SUZ12, leading to the hypomethylation of H3K27 target genes, including Notch, thereby contributing to oncogenesis." (PMID 36135315, 2022).
cardiac hypertrophy (4 papers, 2020 to 2025). "It has been reported that cardiac hypertrophy can be accelerated by loss of Mettl5 through epitranscriptomic regulation of SUZ12 expression." (PMID 40391221, 2025). "In this study, our data indicated that the enhanced cardiac hypertrophy was mainly mediated by the decreased translation of SUZ12 mRNA in METTL5-depleted cardiomyocytes." (PMID 35295259, 2022). "Ahit serves as a scaffold to guide the SUZ12 to the promoter of MEF2A (a critical inducer of cardiac hypertrophy), leading to repressive H3K27me3 and decline in MEF2A expression." (PMID 35990951, 2022). "We show that METTL5 promotes stress-induced cardiac hypertrophy mainly via regulating the translation of SUZ12 mRNA." (PMID 35295259, 2022). "Our data indicated that SUZ12 is an important regulator mediating the inhibitory function of METTL5 in cardiac hypertrophy." (PMID 35295259, 2022). "Forced expression of METTL5 in cardiomyocytes repressed cardiac hypertrophy via modulating the translation of SUZ12 mRNA." (PMID 35295259, 2022). "To validate the role of SUZ12 in METTL5-mediated inhibition of cardiac hypertrophy, we performed a rescue experiment by knocking down SUZ12." (PMID 35295259, 2022). "Furthermore, the partial rescue effect in cardiac hypertrophy was also observed in the treatment of SUZ12/PRC2 inhibitors, EED226 and Boc-NH-C4-acid, during METTL5 overexpression." (PMID 35295259, 2022). "Given that PRC2 complex has been recently reported to participate in regulating cardiac hypertrophy, our data could suggest that SUZ12 was a key upstream regulator mediating the METTL5-related cardiac phenotype observed above." (PMID 35295259, 2022). "Taken together, our results suggested that the SUZ12(PRC2)-Mef2d axis could be critical in the regulation of cardiac hypertrophy by METTL5 mainly through modulating the translational efficiency of SUZ12 mRNA." (PMID 35295259, 2022). "Therefore, we suspected that METTL5 regulated the translational efficiency of SUZ12 mRNA in cardiac hypertrophy." (PMID 35295259, 2022). "Next, we asked how METTL5 regulated the SUZ12-mediated signaling in cardiac hypertrophy." (PMID 35295259, 2022). "A new report revealed that SUZ12 (Suppressor of Zeste 12 Protein Homolog) could mediate the downregulation of myocyte enhancer factor 2A, thereby preventing cardiac hypertrophy." (PMID 32620106, 2020). "Mechanically, METTL5 can modulate the mRNA translation of SUZ12, a core component of PRC2 complex, and further regulate the transcriptomic shift during cardiac hypertrophy." (PMID 35295259, 2022).
non-small cell lung carcinoma (4 papers, 2016 to 2025). A group of at least three distinct histological types of lung cancer, including non-small cell squamous cell carcinoma, adenocarcinoma, and large cell carcinoma. "Furthermore, the suppressor of zeste-12 protein (SUZ12) is of great importance in the tumourigenesis of several human cancers and is involved in the progression of non-small cell lung cancer via its role in promoting cell proliferation and metastasis." (PMID 27010768, 2016).
overgrowth syndrome (4 papers, 2022 to 2024). A group of syndromes caused by genetic birth defects that may lead to the development of malignancies. "As neurological issues have also been observed in Weaver and other overgrowth syndromes, this argues in favour of the implication of SUZ12 in learning disabilities in NF1 deletion patients." (PMID 38448973, 2024). "EZH2, EED, and SUZ12 are components of the polycomb repressive complex 2 (PRC2), and this likely explains why genetic changes in these genes cause similar overgrowth syndromes." (PMID 36927955, 2023).
uterine tumors (4 papers, 2018 to 2022). "It is currently unknown why these fusions are associated with uterine tumors, let alone with new pathogenic subgroups of ESS, but it is intriguing that two of these known JAZF1 fusions (with PHF1 or SUZ12) could directly alter PRC2 function." (PMID 35328741, 2022).
breast tumors (3 papers, 2009 to 2025). "Comparison of the Suz12-deleted gene expression signatures derived for both basal and luminal organoids showed that they were most similar to claudin-low and normal-like breast tumors, similar to that observed for the basal/MaSC cell signature." (PMID 30080881, 2018). "While SUZ12, RBBP4 and RBBP7 were highly expressed in breast tumors, their transcription levels were either comparable to or lower in TNBC groups compared to non-TNBC groups." (PMID 41413688, 2025). "SUZ12 is required for the histone methyltransferase activity and silencing function of the EED–EZH2 complex and is upregulated in different tumors, including breast tumors." (PMID 19250546, 2009).
developmental delay (3 papers, 2021 to 2025). "Comparative analysis of such atypical NF1 deletions suggests that SUZ12 hemizygosity is likely to contribute significantly to the reduced cognitive abilities, severe global developmental delay and facial dysmorphisms observed in patients with type 1 NF1 deletions." (PMID 34681033, 2021).
endometriosis (3 papers, 2017 to 2023). The growth of functional endometrial tissue in anatomic sites outside the uterine body. "Seven genes, namely, APPL1, CSNK2A1, ERG, KDM4A, SMARCC1, SUZ12 and TRIM25, were selected to establish the diagnostic model for endometriosis, and a nomogram was constructed based on them." (PMID 36860677, 2023). "When compared to the EuN tissues, expression of all three PRC2 protein complex (SUZ12, EED and EZH2) and JARID2, was higher in both the eutopic (EuE) and ectopic (EcE) tissue from endometriosis patients." (PMID 33800594, 2021). "DZNep also significantly abrogated the expression of EZH2, EED, SUZ12, H3K9me3 and H3K27me3 in eutopic/control endometrial epithelial cells from mice with or without induced endometriosis, all in a dose-dependent manner." (PMID 28754964, 2017). "qPCR was used to determine the mRNA expression of PRC2 components SUZ12, EED, and EZH2 in eutopic tissue from women with no endometriosis (EuN, n = 5) or women with endometriosis (EuE, n = 10) and ectopic tissue from women with endometriosis (EcE, n = 6)." (PMID 33800594, 2021).